IL18 (interleukin 18)
Diseases named in the same sentence as IL18 in open-access papers (continued):
Sharing a sentence is not in itself a finding about the gene and the disease.
Thrombocytopenia (15 papers, 2011 to 2026). A reduction in the number of circulating thrombocytes. "Of note, infected IFN-γ-deficient mice, as well as IL-12p40−/− and IL-18−/− infected mice, presented elevated viral loads, in parallel with elevated hematocrits, thrombocytopenia, and liver injury." (PMID 22206036, 2011). "This programmed cell death induced thrombocytopenia and inflammatory cytokine release such as IL‐1β and IL‐18, promoting platelet aggregation, vaso‐occlusion, endothelial permeability and cascaded inflammatory response." (PMID 36852778, 2023). "IL-18 shares similar characteristics with IL-1β and is increased in septic patients, particularly in those with thrombocytopenia." (PMID 36439175, 2022). "RANTES (CCL5) levels were significantly decreased in patients, demonstrating severe thrombocytopenia (median 20,767 pg/mL compared to 40,056 pg/mL), while IL-18 levels were significantly increased in these patients (677.9 vs. 448.1 pg/mL)." (PMID 35891358, 2022). "In septic patients, and similar to IL-18, thrombocytopenia has been demonstrated as an independent and complementary risk factor for mortality in multiple studies." (PMID 32998441, 2020). "The mean serum level of IL-18 in patients with CNS involvement, cardiac involvement, leukocytopenia or thrombocytopenia was significantly higher when they had kidney involvement than SLE patients without renal involvement, even if it was higher than controls." (PMID 27047807, 2016). "Although the degree of thrombocytopenia was similar in both strains of mice, hemoconcentration was greater in IL-18−/− than WT infected mice." (PMID 22206036, 2011). "A recent study showed that septic patients with thrombocytopenia had increased plasma and miRNAs expression levels of IL-18 and decreased expression of miR-130a, suggesting that miRNAs were involved in the pathophysiology of sepsis-associated thrombocytopenia and hence, a potential biomarker." (PMID 29207683, 2017). "Moreover, treatment of IL-12p40−/− with IL-18 bp resulted in thrombocytopenia, which was similar to that observed in IL-12p40−/− or IL-18 bp-treated mice, and hemoconcentration, which was greater than in the other groups." (PMID 22206036, 2011). "With the activation of caspase‐1 and the release of inflammatory cytokines such as IL‐1β and IL‐18, one of the hypotheses of thrombocytopenia is that pyroptosis is one of the cell death pathways of platelets, which may be an important intervention and therapeutic target of inflammation." (PMID 36852778, 2023). "Moreover, lymphopenia and thrombocytopenia were observed at the later stages of disease together with sharp increases in plasma levels of proinflammatory cytokines (IL-1β, IL-18, IL-6, and IFNα) and chemokines (I-TAC, MCP-1, and eotaxin), also characteristic of EHF." (PMID 28852031, 2017). "The CRS was evidenced by raised inflammatory markers, thrombocytopenia, elevated cytokine levels (IFN-γ/IL-2R/IL-18/IL-16/IL-10) and steroid responsiveness." (PMID 34040262, 2021). "Au and colleagues presented a patient with fever, thrombocytopenia, CRP increase and elevation of several cytokines including interferon-γ, sIL-2R, IL-18, IL-16 and IL-10 after vaccination and ICI therapy compared to cytokine levels before initiation of ICI therapy and vaccination." (PMID 35715501, 2022).
acute myeloid leukemia (14 papers, 2017 to 2025). Acute myeloid leukemia (AML) is a group of neoplasms arising from precursor cells committed to the myeloid cell-line differentiation. "Only IL-1 and IL-18 polymorphisms in hematological malignancies were linked to clinical and pathophysiological traits in acute myeloid leukemia (AML) and chronic myeloid leukemia (CML)." (PMID 37715239, 2023). "Specifically, genetically predicted higher levels of circulating IL-18 was associated with a decreased risk of acute myeloid leukemia (OR=0.55, 95% CI: 0.43-0.69, P=5.39×10-7, per 1 standard deviation (SD) increase)." (PMID 35865545, 2022). "The interleukin family, particularly IL-18, plays a crucial role in acute myeloid leukemia (AML) and its associated complications, such as GVHD." (PMID 40943537, 2025). "Moreover, genetic polymorphisms of IL-18 were linked with the prognosis and survival of patients with acute myeloid leukemia (AML)." (PMID 31492049, 2019). "However, the HDAC inhibitors NaB, TSA, and valproate regulated the expression of IL-18, a cytokine with antitumor and inflammatory regulatory properties in human acute myeloid leukemia cell lines." (PMID 28460447, 2017). "High IL1RAP expression is associated with poor overall survival in acute myeloid leukemia (AML) patients; although several receptors genes were increased here, only IL18 genes were significantly up-regulated." (PMID 30061915, 2018). "Romee, Fehniger and colleagues demonstrated that stimulation with the cytokines interleukin-12 (IL-12), IL-15, and IL-18 produces so-called cytokine-induced memory-like (CIML) NK cells that exhibited a 56% overall response rate and 44% complete response rate in treatment of acute myeloid leukemia." (PMID 35185932, 2022).
acute pancreatitis (14 papers, 2012 to 2025). An acute inflammatory process that leads to necrosis of the pancreatic parenchyma. "A comprehensive systematic review and meta‐analysis of the genetic evidence for acute pancreatitis was conducted, and identified credible associations of SPINK1, ALDH2, IL1B, IL6 and IL18 with the risk of acute pancreatitis." (PMID 32011822, 2020). "ROS produced by acute pancreatitis stimulate NF-κB, leading to excessive release of cytokines such as interleukin-1β (IL-1β), interleukin-2 (IL-2), interleukin-18 (IL-18), interleukin-6 (IL-6), and TNF-α." (PMID 40411704, 2025). "In a rat model of liver injury associated with severe acute pancreatitis, the inhibitor AG490 of JAK2 effectively reduced the serum levels of TNF, IL-6, and IL-18 by blocking excessive JAK2 and STAT3 activation." (PMID 38543164, 2024). "Here, we demonstrate that serum activin is elevated and strongly correlates with disease severity in two established murine models of acute pancreatitis induced by either cerulein or IL-12 + IL-18." (PMID 28986573, 2017). "In a study focusing on patients with acute pancreatitis, it was demonstrated that higher serum IL-18 levels corresponded to pancreatitis complicated by pancreatic necrosis and remote organ failure showing that pyroptosis was increased in the organs of these patients." (PMID 38585277, 2024). "During the first phase of acute pancreatitis, cytokine pro-inflammation, as TNF (tumor necrosis factor) α, interleukins (IL-1, IL-2, IL-18, IL-6) and chemokine, oxygen radical oxidant are released." (PMID 34036463, 2021). "Disulfiram effectively suppressed the cleavage of GSDMD, ameliorated the development of caerulein‐induced severe acute pancreatitis (SAP) and the corresponding lung injury, and notably attenuated the expression levels of the pro‐inflammatory cytokines IL‐1β and IL‐18." (PMID 40801277, 2025). "Another study found that TLR4-positive acinar cells respond to LPS by activating the inflammasome and producing TNF-α, IL-6, IL-10, IL-1β, IL-18, and MCP-1 during acute pancreatitis, and these effects could be exacerbated by alcohol." (PMID 38585277, 2024).
cardiomyopathy (14 papers, 2010 to 2024). A disease of the heart muscle or myocardium proper. "As additional original findings, our data showed that the IL17A −152 AA and the IL18 −607 AA genotypes are associated with a reduced risk of developing cardiomyopathy in individuals affected by this illness." (PMID 33193300, 2020). "Herein we investigated potential associations between IL1B, IL6, IL17A, or IL18 polymorphism profiles and cardiomyopathy or T. cruzi parasitemia, as well as the impact of HIV infection on cardiopathy." (PMID 33193300, 2020). "Standing as a novel observation, we showed association between the IL18 −607 AA genotype and decreased risk of developing cardiomyopathy, progressing to NYHA ≥ 2, and progressing to LVEF < 45%." (PMID 33193300, 2020). "Original findings included associations between IL17A rs2275913 AA and IL18 s1946518 AA genotypes with decreased risk of developing cardiomyopathy (OR = 0.27, 95% CI 0.07–0.97, P = 0.044; and OR = 0.35, 95% CI 0.14–0.87, P = 0.023, respectively)." (PMID 33193300, 2020). "A potential benefit of targeting IL-18 as a therapy in Chagas cardiomyopathy has been proposed based on the observed association between the IL18-607 AA genotype (to which low IL-18 production is associated) and decreased risk of developing cardiomyopathy in Chagas disease patients." (PMID 39119291, 2024). "Facing the biological and clinical scenarios just described, in the current study we investigated potential associations between SNVs linked to IL1B, IL6, IL17A, or IL18 and the risks of positive T. cruzi parasitemia or development/progression of cardiomyopathy." (PMID 33193300, 2020). "IL-18 may be a novel marker for evaluating ERT efficacy, and targeting IL-18 might be a potential adjunctive therapy combined with ERT for the treatment of advanced cardiomyopathy in FC patients with IVS4+919 G>A mutation." (PMID 27888626, 2016). "Among these subsets of genes that were highly expressed in FC-iPSC-CMs, IL-18 was the most upregulated genes expressed in FC-iPSC-CMs, raising the possibility that interleukin-18 (IL-18) may act as a potential biomaker in FC-associated cardiomyopathy." (PMID 27888626, 2016). "We also describe novel associations between specific IL18, IL17A, and IL1B variant profiles and the risk of cardiomyopathy as well as between a specific IL6 polymorphic genotype and the risk of positive T. cruzi parasitemia." (PMID 33193300, 2020). "Among studied cytokines, some were associated with general susceptibility to T. cruzi infection (IFN-γ, MIF, IL-4, TNF, TGF-β, and IL-18) and others with cardiomyopathy development (TNF, IL-1, BAT1, MCP-1, LT-α, IL-12, and IL-10)." (PMID 29670670, 2018). "Collectively, these studies demonstrated the protective effect of IL-18 neutralizing molecules, i.e. anti-IL-18 antibody or IL-18BP, on experimental models of cardiomyopathy." (PMID 27888626, 2016). "In addition, in our in vitro iPSC-CM model, the combination of ERT plus IL-18 neutralization effectively ameliorated and prevented the progression of hypertrophy and cardiomyopathy in hypertrophic FC-iPSC-CMs." (PMID 27888626, 2016). "Both HIV-associated cardiomyopathy and chronic heart failure have been associated with activation of the immune system leading to the pathogenic overproduction of several proinflammatory cytokines, including TNF-α, IL-1β, IL-6 and IL-18." (PMID 21203448, 2010). "In addition, the IL18 rs2043055 G allele was found to associate with absence of cardiomyopathy in Colombia." (PMID 33193300, 2020). "Moreover, other SNP related to other cytokines that could be related to susceptibility to T. cruzi infection (IFN-γ, MIF, IL-4, TNF, TGF-β, and IL-18) or cardiomyopathy development (TNF, IL-1, BAT1, MCP-1, LT-α, IL-12, and IL-10) were not studied." (PMID 29670670, 2018). "Daily IL-18 administration has been reported to induce myocardial dysfunction in BALB/c mice, and interferon therapy can lead to reversible cardiomyopathy." (PMID 35069538, 2021).
emphysema (14 papers, 2011 to 2021). "Cigarette-smoke-induced inflammation and emphysema in the lung of wild-type mice were also associated with an increase in IL-18 expression." (PMID 27001429, 2016). "Both IL-18 and IFNγ have been reported to contribute to emphysema pathogenesis in mouse smoke, and increases in lymphoid aggregates are reported in mouse smoke models in a similar timeframe to emphysema progression." (PMID 28830544, 2017). "Although IL-18 knockout mice exhibit reduced pulmonary inflammation and emphysema compared to wild-type mice after cigarette smoke, pulmonary inflammation occurred independent of NLRP3/caspase-1 axis after four weeks of cigarette smoke exposure." (PMID 28056996, 2017). "Tumor necrose factor (TNF) –α, interferon-γ and various classes of interleukins as the IL-1β, IL-6, IL-8, IL-10, IL-17, IL-18, IL-32 and others are involved in the progression of emphysema." (PMID 27775634, 2016). "Recently, it has also been reported that overexpression of IL-18 induced emphysema via IFN-γ and IL-17A, and induced mucus metaplasia via IL-13." (PMID 23331548, 2013). "As we previously reported, very severe pulmonary inflammation and emphysema are induced in C57BL/6 lung-specific IL-18 Tg mice and recently, Elias and his colleagues reported similar results." (PMID 23382928, 2013). "The inducible expression of IL-18 in the lungs induces pulmonary inflammation, emphysema, mucus metaplasia, airway fibrosis, vascular remodeling and right ventricle cardiac hypertrophy in adult B6 mice using the CC10 promoter." (PMID 23382928, 2013). "Severe pulmonary inflammation and emphysema were observed in the lungs of B6 IL-18 Tg mice as we previously reported." (PMID 23382928, 2013). "Previously, we showed that constitutive overproduction of mature IL-18 protein in the lungs of transgenic mice resulted in severe emphysema accompanied by pulmonary inflammation." (PMID 21915293, 2011). "In addition, disruption of the IL-17 gene prevented emphysema and pulmonary inflammation in the B6 IL-18 Tg mice." (PMID 23382928, 2013). "It has been shown that the expression of IL-18 in the mature murine lung induces inflammation that is associated with the accumulation of CD4(+), CD8(+), CD19(+), and NK1.1(+) cells; emphysema; mucus metaplasia; airway fibrosis; vascular remodeling; and right ventricle cardiac hypertrophy." (PMID 23956502, 2013). "Furthermore, IL-18 knockout mice show significantly decreased inflammation and emphysema compared to wild-type mice following CS exposure; whereas mice over-expressing IL-18 in the lung display a COPD-like phenotype." (PMID 21915284, 2011). "Furthermore, future studies on blocking the lymphocyte inflammation or IL-18/IFN-γ signaling to ameliorate the emphysema phenotype in Hhip+/– murine models and examination of expression of IL-18 in human lung tissue are also warranted to pinpoint the therapeutic applications." (PMID 34375314, 2021). "However, they may also contribute to emphysema progression, particularly since the localised effects of IL-18 on tissue resident responder cells may be to increase IFNγ without the requirement for cognate antigen." (PMID 28830544, 2017). "Furthermore, when either IL-1β and IL-18 is over expressed it leads to emphysema/COPD." (PMID 25405768, 2014). "Thus, we believe that localized production of IL-18 in the lungs may play an important role in the development of pulmonary inflammation and emphysema via IL-13 production in mice as well as COPD patients." (PMID 23382928, 2013). "The relative mRNA levels of TNF-α, IFN-γ, IL-8, IL-18, IRF-5, and TGF-β increased in the emphysema mice." (PMID 32681029, 2020). "Similarly, IL-18, a strong inducer of IFN-γ, not only promotes emphysema development in murine models but also functions as a biomarker and a master cytokine driving COPD progression." (PMID 34375314, 2021).
emphysema (continued). "Importantly, the mRNA levels of IL-1β, TNF-α, IL-8, IRF-5, IL-18, IFN-γ, TGF-β, matrix metalloproteinase-9 (MMP-9), and MMP-12 were decreased in the FMT-treated emphysema group compared with the emphysema group." (PMID 32681029, 2020). "Furthermore, overexpression of IL-18 in mice drives inflammatory cell accumulation (primarily CD8+ T cells, macrophages, neutrophils and eosinophils) resulting in severe emphysema and airway fibrosis." (PMID 27001429, 2016). "Previously, we showed that constitutive overproduction of mature IL-18 protein in the lungs of B6 background transgenic mice resulted in the increased production of IFN-γ IL-5, and IL-13, and severe emphysema accompanied by pulmonary inflammation, especially by CD8+ T cells." (PMID 23382928, 2013). "Moreover, the mRNA expression of other representative proinflammatory mediators, including IL-1β, tumor necrosis factor-α (TNF-α), IL-8, IL-18, and immune modulators, such as interferon regulatory factor-5 (IRF-5) and transforming growth factor-β (TGF-β), was increased in emphysema mice." (PMID 32681029, 2020). "Moreover, disruption of the IL-13 but not IFN-γ gene prevented emphysema and pulmonary inflammation in IL-18 Tg mice." (PMID 23382928, 2013). "Moreover, disruption of the IL-13, IL-17 gene, but not the IFN-γ gene prevented emphysema and pulmonary inflammation in IL-18 Tg mice." (PMID 23382928, 2013).
kidney injury (14 papers, 2013 to 2025). Trauma to the kidney. "Urine samples were collected and six urine biomarkers (calbindin, clusterin, GST-π, IL-18, KIM-1, MCP-1) associated with kidney injury were assessed using the Bio-Plex Pro RBM Human Kidney Toxicity Assays kit (Bio-Plex Manager software 4.0)." (PMID 40650014, 2025). "As well, we were unable to compare with other markers of acute kidney injury—such as kidney injury molecule 1 (KIM-1), interleukin-18 (IL-18), and neutrophil gelatinase-associated lipocalin (NGAL)—as these were not determined in the PROMISE cohort." (PMID 38352963, 2024). "Studies have shown that IL-18 increases faster than serum creatinine in AKI (83.8% of patients had an increase in IL-18 value 24 h after kidney injury compared to 6.7% of patients who had an increase in serum creatinine)." (PMID 37363465, 2023). "Thirdly, it has been reported that some novel biomarkers (interleukin 18 and kidney injury molecule‐1) could predict the occurrence of subclinical kidney injury, which can act as a promising tool to improve the early diagnosis." (PMID 32400109, 2020). "IL-18 is known to promote inflammation and immunity through its key cellular targets including macrophages, T cells, and NK cells, which leads to inflammation and subsequent kidney injury." (PMID 26990190, 2016). "The discriminate rise of IL-18 in cortex and drop in medulla of dehydrated and rehydrated camels compared to controls might indicate that the kidney cortical cells independent of macrophage might be the source of IL-18 productions similar to that observed in obstructive kidney injury." (PMID 33228660, 2020). "Neutrophil gelatinase-associated lipocalin (NGAL), kidney injury molecule-1 (KIM-1), interleukin-18 (IL-18), and cystatin C (CysC) are some of the new biomarkers that have shown promise in early AKI detection and in differentiating structural from functional kidney injury." (PMID 40868897, 2025).